TNF (tumor necrosis factor)
Diseases named in the same sentence as TNF in open-access papers (continued):
Sharing a sentence is not in itself a finding about the gene and the disease.
infection (continued). "We measured the serum cytokine response 7 d post-infection and saw a decrease in TNF-α and IFN-γ in Meloxicam-treated mice infected with parental strain compared to untreated." (PMID 37646522, 2023). "Here, we provide evidence of different signaling for cancer progression and invasion of human gastric organoids in response to HDGF and TNFα during infection by H. pylori." (PMID 37047540, 2023). "At 60 days post infection, there was also a trend toward decreased TNF+ DC in mice transferred Tregs from either air- or CS-exposed mice." (PMID 37965256, 2023). "TNF-α is a crucial pro-inflammatory cytokine in reaction to an infection by bacteria which is produced by neutrophils." (PMID 37538167, 2023). "C. burnetii-infected bovine macrophages were also characterized by an upregulation of TNFα and IL-10 at early time-points post-infection." (PMID 36793725, 2023). "Compared to uninfected cells, B. pseudomallei K96243 infection stimulated IL-8 and TNF-α at 8 h post-infection with an average production of 382.64 ± 7.37 pg/mL and 1.77 ± 0.20 pg/mL, respectively." (PMID 38001928, 2023). "The mRNA levels of IL-1β and TNF-α in lungs were all significantly down-regulated by the melatonin administration at day 6 and/or day 9 post-infection compared to the infected control mice (P < 0.05)." (PMID 37200384, 2023). "BAL cytokines that were elevated peaked at mid-infection (42 days post inoculation) included, IL-6, IL-12, IFNγ, TNF, MIP-1β." (PMID 36893126, 2023). "Inflammatory MoDCs are multifunctional and express IL-1α, IL-1β, IL-10, TNF-α, and inducible nitric oxide synthase (iNOS) in the lungs between 2 and 3 weeks after infection with M. tuberculosis." (PMID 37686061, 2023). "The Evans blue units, TNF-α and IL-1β levels were significantly increased in the infection groups compared with the control group; however, their levels were significantly decreased in the ABZ plus calycosin treatment group." (PMID 36341547, 2023). "In the liver, samples were grouped according to the day of infection (Groups A and C = day 3 p.i.; Groups B and D = day 4 p.i.), although they were still separated according to anti-TNF-α Ab treatment." (PMID 37939119, 2023). "Upon infection of the periodontal tissue by periodontal pathogens, macrophages produce proinflammatory cytokines like IL-1, IL-6, and TNF-α, which play crucial roles in regulating the inflammatory response to combat the infection." (PMID 37509571, 2023). "RT-PCR data showed that the titers of all three inflammation-related genes (IL-6, IL-1β, and TNFα) were upregulated upon SARS-CoV-2 Delta-spike PV infection and decreased upon treatment with compounds K-4 and M-4." (PMID 36855173, 2023). "TNFα and IL1β play an important role in regulating innate immune systems against infection and other stress condition." (PMID 36977939, 2023). "Infants of patients on combined anti-TNF + immunomodulator therapy exhibited higher infection rates during their first year, likely due to the combined immunosuppressive effect." (PMID 37834837, 2023). "GM-CSF-deficient mice exhibits increased fungal burden and aberrant lung function post infection, due to the decreased phagocytosis and TNF-α production in AMs." (PMID 37359523, 2023). "The depletion of neutrophils, during early infection, leads to a Th2 response, since the decreased levels of IFN-γ, IL-12, and tumor necrosis factor- α (TNF-α) lead to a weaker Th1 response, increasing susceptibility." (PMID 37112645, 2023). "In the early stage of bacterial infection, the mobilization and recruitment of neutrophils by inflammatory chemokines, stimulated by TNFα, plays an important role in anti-infection." (PMID 39619227, 2023). "The mRNA expression levels of IL-6, IL-18, IFN-α, IFN-β, and ISG-15 were up-regulated during EV-G/YN23/2022 infection, while IL-1β, TNF-α, IFN-λ3, and IRF-7 maintained in relatively constant levels, and no cytokines were significantly reduced." (PMID 37632087, 2023).
infection (continued). "CD8+ T cells also play an indispensable role in the process of adaptive immunity against infections via synthesizing pro-inflammatory cytokine IL-17 and producing cytokines, including TNF-α and IFN-γ." (PMID 37893490, 2023). "IL-6 and TNF-α are classified as pro-inflammatory cytokines that neurons and other cells can discharge in reaction to stimuli such as injury, infection, or stress." (PMID 37987444, 2023). "TNF‐α is a pluripotent and proinflammatory cytokine produced by activated macrophages, and TNF‐α induces the production of other cytokines, such as IL‐6, during infection, thereby increasing leukocyte accumulation and amplifying the inflammatory cascade." (PMID 37644785, 2023). "During infection with hepatotropic viruses, the long-term production of Il-6, IL-8, and TNF-α leads to the generation of free radicals." (PMID 37507865, 2023). "Our work shows that TNF protects macrophage populations from L. pneumophila by licensing cells to rapidly self-sacrifice upon infection and limit the replicative niche of the bacteria." (PMID 37279255, 2023). "BCG infection significantly stimulated both splenic cDC and pDC to produce IL-6, IL-10, IL-12p70, MCP-1, and TNF-α, especially at 4 h and 12 h post-infection, whereas naive DCs secreted negligible amounts of these cytokines." (PMID 36977141, 2023). "The thymus involution during infection is also attributed, at least partially, to the increased levels of TNFα and IFNγ." (PMID 38140683, 2023). "Curcumin significantly reduces TNF-α levels during the early stages of infection, especially in the spleen and lungs." (PMID 38067016, 2023). "ELISA measurements indicated enhanced expression of CCL28, IL-1β, IL-6, and TNF-α following infection with Adv-CCL28, compared with Adv-Ctl." (PMID 36713846, 2023). "Since TNFα promotes cell death via necroptosis, we evaluated necroptosis in cardiac fibroblasts after infection with WT and M45mutRHIM CMV." (PMID 37012234, 2023). "Significantly higher SARS-CoV-2 antigen-specific IgG, IFN-γ, IL-5, TNF-α, and IL-6 levels occurred in the breakthrough infection group compared to the booster immunization group (p = 0.013, 0.039, 0.024, 0.017, and 0.039, respectively)." (PMID 37515030, 2023). "In our cohort, the presence of antibodies is less likely among those treated with anti-TNF than with other biologics and, overall, there is less seroconversion after known infection than in the general population." (PMID 37120662, 2023). "TNF-α, IL-10, IL-13, and IL-33 were significantly (p < 0.05) increased in severe infection comparison to a mild infection in children with HRSV coinfection with HBoV." (PMID 37239461, 2023). "Of note, TNF-dependent restriction was apparent only after 24 hours post-infection, indicating that endogenous TNF produced in response to the initial infection was responsible for mediating restriction of L. pneumophila at later timepoints." (PMID 37279255, 2023). "Calu-3 cells were infected with virus and were left untreated (control) or treated with IFN-ß and TNF-α before (Pretreated) or after (Posttreated) infection." (PMID 36610792, 2023). "TNF-mediated increase in Casp11 transcription can still be observed at 16 hours following priming (at the time of infection), while Il1a and Il1b transcription fades by that time." (PMID 37279255, 2023). "We found different signaling of cytotoxicity and invasion of human gastric organoids in response to HDGF and TNFα during infection by H. pylori." (PMID 37047540, 2023). "The levels of Th1-type cytokines (IFN-γ, TNF-α) and immune inhibitory cytokines (IL-10) in Tigit-/- mice were higher than those in WT mice at 4 and 6 weeks after infection." (PMID 36930687, 2023). "Key innate inflammatory cytokines, including TNFα, IL-6, IFNα, IL-10, IL-15, and IL-18, were all significantly elevated early during infection (days 1–5) compared to HCs." (PMID 36752598, 2023).
infection (continued). "As expected, the IL-6 and TNF-α secretion induced by LPS were also significantly inhibited by CVB3 pre-infection." (PMID 37243164, 2023). "Treatment with M220+CQ significantly decreased the number of macrophages, DCs, neutrophils, and Ly6Chi monocytes producing TNF in the brain during PbA infection." (PMID 38256880, 2023). "Infection by T. rubrum was shown to stimulate the activation of nuclear factor kappa beta (NF-κB) and the production of IL-1β, IL-6, TNF-alpha and IL-10 by macrophages." (PMID 36838531, 2023). "Since NK cells are the first proliferating lymphocyte population during infection and inflammation and proliferation is hardwired to effector function, the effect of TNFα on NK cells is critical to our understanding of NK cell antiviral and antitumor activity." (PMID 37553427, 2023). "Apoptosis inducers (H2O2, ActD, cMYC inhibitor, and TNF-α+SM-164 [T/S]) were added to the cells at different infection stages." (PMID 36744941, 2023). "Flow cytometry and RT-qPCR showed that the levels of effector molecules in hepatic NK cells, such as IFN-γ, Prf1, Gzmb, IL-10, and TNF-α, were higher in Tigit-/- mice than in WT mice at 4 and 6 weeks post infection." (PMID 36930687, 2023). "The higher levels of neutrophils, NO, IL-6, and TNF-α in lesions contaminated by S. aureus demonstrate this deleterious role of infection during the inflammatory phase." (PMID 36770872, 2023). "M1 macrophages produce pro-inflammatory cytokines, such as IL-1β, IL-6, IL-12, and TNF-α, which help to activate and recruit other immune cells to the site of infection or tissue injury." (PMID 37507898, 2023). "Compared to cells cultured with DMSO, GFs cultured in the presence of DAC released at least 10-fold higher amounts CCL20 upon infection with P. gingivalis or stimulation with TNF or IL-1β." (PMID 36776856, 2023). "These TNF-α preprogrammed DCs generate a protective Th1 polarized CD4+ T cell response during infection." (PMID 37998856, 2023). "By quantitative RT-PCR (qRT-PCR), we confirmed that IL-6, IL-1β, and MMP-8 mRNAs were commonly upregulated in the liver and small intestine after infection and were all suppressed by anti-TNF-α Ab treatment." (PMID 37939119, 2023). "TNF alpha is a pro-inflammatory cytokine produced by the body as part of the normal immune response to pathogens and infections." (PMID 37065345, 2023). "Markers IL-1β, IL-6 and TNF-α also decreased following polymicrobial infection as compared to single-species P. aeruginosa infection, which was significantly higher than uninfected controls (****P<0.0001)." (PMID 36748431, 2023). "We further analyzed the active status of infiltrated immune cells during infection by measuring the levels of pro-inflammatory markers such as IFNγ, TNFα, and IL-6 in the lungs by Western blotting." (PMID 36676177, 2023). "Following NE infection in broiler chickens, the proinflammatory factor TNF-α increased and the anti-inflammatory factors IL-4 and IL-10 decreased, disrupting the dynamic balance and promoting inflammation." (PMID 37508014, 2023). "After infection, pro-inflammatory cytokines, such as tumor necrosis factor-α (TNF-α) and interferon-γ activate macrophages, produce ROS and reactive nitrogen species (RNS) regulated by the expression of nitric oxide synthase (NO)." (PMID 37110466, 2023). "For example, the expression of interferon (IFN)ß and tumor-necrosis factor (TNF)α is upregulated in fibroblasts and keratinocytes upon infection." (PMID 37363242, 2023). "Our results show a critical role of early acute TNFα production within the first hour after the infection before the reported IL6 and IL10 production in both experimental and clinical studies." (PMID 37520526, 2023). "Treatment of mice with DSS and infection with parasites resulted in increased levels of IL-6, TNF-α, and IL-10 in serum; IL-1β and IL-6 in the colon; and IL-6 in the small intestine." (PMID 36836678, 2023).
infection (continued). "Pro-inflammatory cytokines TNF-α, IL-6, IL-1β expression increased two days post infection (dpi) and contributed to the virus clearance from infected goats." (PMID 37764982, 2023). "Studies show that host cells infected with C. trachomatis release this pro-inflammatory cytokine throughout the growth cycle of C. trachomatis which, along with the release of TNF and IL-10, leads to a poorer prognosis of the infection." (PMID 36897879, 2023). "Since TNF-β is the closest family member to TNF-α, XPro-1595’s ability to readily interact with solTNF ensures its potential clinical safety, preserving tmTNF’s role in immune function and infection control." (PMID 38036985, 2023). "Adoptive transfer of CD4+ T cells from the airways of RSV-infected mice into naïve mice reduced disease severity by suppressing the secretion of TNF-α compared to control mice, further supporting their protective role during infection." (PMID 37896776, 2023). "We found that infection with Mycobacterium avium impacts bone turnover by decreasing bone formation and increasing bone resorption, in an IFNγ- and TNFα-dependent manner." (PMID 37153579, 2023). "The results revealed that CXCL8 and CXCL10 cytokine expressions were significantly increased from 8 h post-infection while TNF cytokine level remained similar after infection." (PMID 37695039, 2023). "Ephedra sinica Stapf polysaccharide, the main component of Ephedra sinica, significantly increased the abundance of Lactobacillales and Bifidobacteriaceae in the intestine of mice 7 days after FM1 infection, and reduced IL-6, IL-8, and TNF-a in lung tissue." (PMID 37928517, 2023). "We observed relatively lower mRNA expression of inflammatory cytokines (IFN-γ, TNF-α, IL-4, IL-6, IL-17A and IL-33) in BA.5 infection as compared to ancestral Wuhan-Hu-1 infection." (PMID 37704701, 2023). "It is also known that during infection, immune system upregulates the concentration of main pyrogenic cytokines such as IL-6, IL-1β and TNF-α that mediate the fever response." (PMID 37849757, 2023). "Curiously, the pyrin domain of C1 alone enhanced cellular responses to TNF-α, which potentially implicates the Bcl-2 domain in a role preventing aberrant activation of cellular inflammatory pathways by C1 during infection." (PMID 37494187, 2023). "Our study explored the role of soluble TNF in controlling M.tb infection dissemination while sustaining both acute and chronic bacterial growth inhibition and T-cell migration to the infection site." (PMID 38036985, 2023). "Blocking TNF cytokine impeded the natural resolution of the infection in the liver (as the immune response is organ specific), which is mediated by granuloma formation, explaining the highest parasite load found in this organ at W6." (PMID 38106411, 2023). "Given that TNFα is a major driver of cachexia during infection, it is paradoxical that it also drives increased expression of these two lipid storage enzymes in NAFLD, suggesting that the role of this cytokine is tissue- and context-dependent." (PMID 37371074, 2023). "In both B6.Nlrc4–/–Casp11–/– and 129.Nlrc4–/– mice, TNFα neutralization led to a striking increase in severity of infection and a 10-fold increase in bacterial colonization of the intestinal epithelium." (PMID 36645406, 2023). "Pathogen-associated specific CD8+T cells, which produce high levels of IL-2, IFN-γ, TNF-α, perforin, and granzyme B to regulate the infection, are essential for HCMV immunity." (PMID 36723437, 2023). "Several infection-induced immune mediators, such as tumor necrosis factor (TNF), IL-6, IL-8, IL-12, IL-23 and IL-1β, intensify the barrier damage." (PMID 36979344, 2023). "Inflammatory cytokines, TNF, interleukin 6 and 1 β (IL-6, and IL-1β) levels increase over the course of infection in specific tissues where pathogen-specific T cells are present." (PMID 36911729, 2023).
infection (continued). "Infections can disrupt the balance of cytokines (TNF-α and IL-1β), serum proteins, and white blood cell functions, all leading to inflammation and disease progression." (PMID 37569767, 2023). "TNF is one of the main proinflammatory cytokines and also plays a key role in response to infection." (PMID 37835065, 2023). "Pro-inflammatory IL-6 was significantly increased in severe infection (p = 0.009) while TNFα was decreased (p = 0.016) compared to healthy controls." (PMID 37598150, 2023). "When infection or inflammation is severe enough to affect an organ, macrophages can first exhibit the M1 phenotype to release TNF-α, IL-1β, IL-12, and IL-23 against the stimulus." (PMID 36636989, 2023). "The effect of preoperative anti-TNF therapy on postoperative infection risk was examined in the PUCCINI trial, in which 947 IBD patients underwent surgery, and anti-TNF use within the previous 12 weeks was reported in 382 individuals." (PMID 38202126, 2023). "Considered a master regulator of the proinflammatory response, TNF, plays a critical role in activating the innate immune system leading to immune cell infiltration at the site of infection or injury." (PMID 38129491, 2023). "The infection decreased total white blood cells, lymphocytes, and the cytokine tumor necrosis factor-alpha level and increased cytokine interleukin-1-beta." (PMID 37627021, 2023). "TNF-alpha (TNFα) is a major contributor to the inflammatory response, regulating various aspects of sickness behavior during infection, including fever and cachexia." (PMID 37371074, 2023). "Generally, IL-8 is known for activating and recruiting neutrophils to sites of infection via the IL-1 and TNF-α signalling pathways." (PMID 36441210, 2023). "We found that infection with E. coli mcr-1+ significantly decreased the secretion of pro-inflammatory cytokines IL-8, IL-1β, and TNF-α (p values, 0.002 to <0.0001)." (PMID 36670449, 2023). "TNF-α expression was significantly upregulated in blood of the large yellow croaker after 2 and 4 dpi with infection with Vibrio parahaemolyticus." (PMID 37569767, 2023). "Once activated, iNKT cells promptly produce various cytokines, including IFNγ, TNFα and IL-10 which actively recruit and activate neutrophils, macrophages, NK cells, and other immune cells to the site of infection." (PMID 37965344, 2023). "In this study, we detected the increased presence of serum cytokines IL-6, TNF-α, and IL-1β after the infection." (PMID 37256132, 2023). "Macrophages also contribute to the ‘early’ release of TNF and other pro-inflammatory cytokines in vivo, which are involved in controlling infection." (PMID 37112697, 2023). "At baseline, WT mice had negligible TNF levels in the skin, which increased upon S. aureus infection on day 1 after infection, peaked on day 3 after infection, and subsided by day 7 after infection." (PMID 37327341, 2023). "The cytokines produced by Th1 cells (IFN-γ, IL-2, IL-12, and TNF-α) can help clear the infection by promoting the activation of macrophages and other immune cells that can eliminate the intracellular pathogens." (PMID 37889704, 2023). "We found the upregulation of IL-12A, IL-12B, and TNF, suggesting a possible involvement of B cells in shaping the splenic type-1 cytokine environment in Ot infection." (PMID 37146079, 2023). "Here we showed that expression of TNF-α was inhibited at all time points while IL-6 was decreased at 48 h post-infection only compared to the control." (PMID 37280772, 2023). "This was unexpected, as both TNF-α and IL-17A/F drive host defense against S. aureus at other infection sites (e.g., skin and orthopedic implants)." (PMID 37483624, 2023). "In our study, TNF- α gene was significantly upregulated in gills at all-time points, particularly at day 14 post-infection, compared to the control." (PMID 37337042, 2023).